ALB (albumin)
Diseases named in the same sentence as ALB in open-access papers (continued):
Sharing a sentence is not in itself a finding about the gene and the disease.
COVID-19 (continued). "By taking the intersection of COVID-19/HCC genes and vitamin D-associated targets, we obtained seven overlapping genes (HMOX1, MB, TLR4, ALB, TTR, ACTA1 and RBP4) of vitamin D against COVID-19/HCC." (PMID 36275701, 2022). "We analyzed the prognostic capacity of serum albumin (SA) and CRP for an outcome comprising mortality, length of stay, ICU admission, and non-invasive mechanical ventilation in hospitalized COVID-19 patients." (PMID 35740416, 2022). "Compared to another study, our study finds similar results that children with severe COVID-19 and MIS-C have low serum albumin levels." (PMID 35855892, 2022). "In all COVID-19 instances, we found a considerable increase in ALT, AST, and CRP, as well as severe albumin depletion." (PMID 36298501, 2022). "COVID19 SEIMC score greater than 10.5 points, CRP/pre-albumin greater than 0.88, and BUN/creatinine greater than 23.98 were also the cut-off points for predicting mortality in COVID-19 patients." (PMID 35807907, 2022). "Consistently with previous studies, we confirmed the importance of known medical and inflammatory markers for severe COVID-19, such as age, body temperature, oxygen saturation, LDH and albumin." (PMID 35173197, 2022). "As revealed by the LogNNet network, the combination of ESR, NEU, CRP, Albumin, RBC, Chlorine, and RDW features is an important source of variation in the prognosis of COVID-19." (PMID 35808317, 2022). "As for our cured COVID-19 patients, their serum ALT, AST, GGT, creatinine, TBIL and DBIL returned to normal; ALB was down-regulated." (PMID 36091834, 2022). "We next carried out further correlation with the three biomarkers, DPP4 (the most differentially regulated protein in the post-COVID-19 BAL), LDH, and albumin, as markers of ongoing damage in the airways." (PMID 35151371, 2022). "Both CRP-to-albumin ratio and CRP-to-lymphocyte ratio showed good performance in assessing 30-day mortality in KTR with COVID-19." (PMID 36556433, 2022). "A retrospective study comprising 2623 confirmed COVID-19 patients with acute hepatic injury revealed that low albumin serum level and high GDF15 serum level are correlated with COVID-19 severity and death." (PMID 36140453, 2022). "Moreover, although glycated albumin reduced the ability of native album to bind the spike S1 subunit protein, future studies are needed to analyze the relationship between the level of glycated albumin and the in-hospital mortality of COVID-19 confirmed patients." (PMID 35160039, 2022). "Multivariate analysis showed that older age, male gender, comorbidities such as DM, active malignancy, white cell count, serum creatinine, albumin, and CRP were independent predictors of hyponatremia in patients with COVID-19 (P < 0.001, for all)." (PMID 36714113, 2022). "Patients with severe COVID-19 had significantly increased ALT, AST, GGT and LDH activities, and decreased albumin levels." (PMID 36289725, 2022). "Next, we further analyzed the possible binding of vitamin D with the seven COVID-19/HCC targets (HMOX1, MB, TLR4, ALB, TTR, ACTA1 and RBP4) identified previously and found that vitamin D only binds to MB and RBP4." (PMID 36275701, 2022). "COVID-19 patients in ICU on TEN had lower APACHE II scores, frequency of feeding suspension and mortality, however, with higher content of albumin was found at 5th day." (PMID 36343035, 2022). "ALB and LDH are considered biomarkers for predicting the COVID-19 severity in the previously published findings." (PMID 36437821, 2022). "We noted that the liver injury-related markers, including decreased pre-albumin, albumin, and cholinesterase levels, were observed at the initial stages, and the intermediate stage of SARS-CoV-2 infection in severe and critical COVID-19." (PMID 34659204, 2021). "We present to you the CAPA score calculated from CRP, age, platelet count, albumin levels, which is an effective score in predicting mortality and ICU admission in COVID-19." (PMID 34784756, 2021).
COVID-19 (continued). "Results of routine tests like LFT, kidney function tests (KFT), glucose, albumin, electrolytes and complete blood count (CBC) were significantly altered in severe or critical COVID-19 patients belonging to the Asian population." (PMID 34760713, 2021). "Previous studies have confirmed that patients with COVID-19 can have abnormal liver function, which is manifested by increased ALT and AST levels and decreased albumin levels, but there are fewer reports of abnormal levels of other indexes." (PMID 34327212, 2021). "We found significantly higher levels of CRP, fibrinogen, ferritin, D-dimer and CPK, and significantly lower albumin levels and total serum protein in MIS-C compared to children with COVID-19." (PMID 34576853, 2021). "The usage rate and the feature importance of the CLIs in the HPCs indicated that PCT, MCHC, uric acid, albumin, AGR, neutrophil count, RBC count, monocyte count, and WBC count are the most important indicators that can distinguish COVID-19 from CAP." (PMID 33534722, 2021). "For all enrolled COVID-19 patients, the levels of ALT, AST, and DBil were gradually increased with increased TOH (p = 0.004, 0.014 and 0.002, respectively), but level of albumin was gradually decreased with increased TOH (p < 0.001)." (PMID 34210280, 2021). "The most common clinical abnormalities observed in COVID-19 positive patients are lymphopenia, leukopenia, thrombocytopenia, elevated CRP and inflammatory markers, elevated cardiac biomarkers, decreased albumin, and abnormal renal and liver function." (PMID 34093642, 2021). "We also found a notable decrease of albumin and increase of CRP in COVID-19 patients, especially in ICU patients, which is consistent with a recent study." (PMID 33640878, 2021). "In our cohort, more severe clinical presentation of COVID-19 at admission was observed among patients with elevated AST, ALT, GGT and low ALP, albumin and PT." (PMID 34575333, 2021). "In the group with COVID-19, alkaline phosphatase (ALP) increased (R = 0.192, P < 0.0001) and albumin declined (R = -0.123, P = 0.0004) over time in patients who died." (PMID 34510830, 2021). "With this study, we present to you the CAPA score calculated from CRP, age, platelet count, albumin levels as an effective score in predicting mortality and ICU admission in COVID-19." (PMID 34784756, 2021). "Overall, it can be observed that the COVID-19 treatment duration is higher for obese patients with high CRP levels and low Albumin levels." (PMID 34207560, 2021). "Univariate logistic regression analysis on the factors that influenced mortality among the COVID-19-positive patients in the ICU, including male sex, cortisol level, CRP level and albumin level, showed significant results." (PMID 34190873, 2021). "After evaluating 189 patients, they showed that age, RDW, BUN, CRP, LDH, ALB and DBIL were predictive factors for severe COVID-19." (PMID 34254030, 2021). "Many studies have confirmed that patients with COVID-19 can have abnormal liver function, which is manifested by increased ALT and AST levels, decreased albumin levels, and increased TBil levels in a few cases." (PMID 34327212, 2021). "Pathway analysis between Ephedra-Glycyrrhiza and COVID-19 showed that the key targets were TNF-α, IL2, FOS, ALB, and PTGS2." (PMID 33581688, 2021). "In the present study of 160 consecutive critically ill COVID-19 patients with moderate to severe ARDS, IL-6, serum albumin, and D-dimer at admission to ICU, accompanied by chest CT severity score, were marked as independent predictors of mortality." (PMID 33968298, 2021). "When stratified according to the severity of COVID-19 (mild vs. severe/critical), the dynamic curves of LFTs showed downward trends of ALT, AST, TBIL, ALP, and GGT and a upward trend of albumin in both mild and severe/critical groups." (PMID 34179034, 2021).
COVID-19 (continued). "Patients followed up in the ICU (severe COVID-19 patients) were found to be older, had higher rates of comorbidity, lower lymphocyte I and II values, higher TLO 1-2, and lower serum albumin levels (P < 0.05)." (PMID 33350294, 2021). "The five most useful routine blood parameters for COVID-19 diagnosis according to the feature importance scoring of the XGBoost algorithm were: MCHC, eosinophil count, albumin, INR, and prothrombin activity percentage." (PMID 34031483, 2021). "When stratified according to the severity of COVID-19 infection, patients with severe or critical COVID-19 had higher median values of AST, TBIL, ALP, and GGT and lower median value of albumin." (PMID 34179034, 2021). "The RRs for severe COVID-19 patients were 1.76 (ALT), 2.30 (AST), 2.31 (GGT), and for albumin, 2.65." (PMID 34287285, 2021). "Previous studies showed that severe or critical COVID-19 patients were older, had more comorbidities, higher levels of LDH, D-dimer, CRP, and lower levels of ALB, lymphocyte count." (PMID 34372792, 2021). "The current study focused on the levels and prognosis of seven indicators including oxygen, lymphocytes, albumin, leukocyte, CRP, IL-6, and D-dimer in COVID-19 patients." (PMID 34778296, 2021). "Compared with patients with mild COVID-19, those with severe COVID-19 had significantly higher levels of TNF-α and NT-proBNP, and lower levels of CD4 T cells and albumin globulin." (PMID 33232275, 2020). "As in the Chinese cohort of 85 fatal cases, our severe COVID-19 patients had comparable laboratory findings: decreased lymphocytes, increased CRP, and decreased albumin." (PMID 32903324, 2020). "ROC curves demonstrated significant predictive value of age, lymphocyte count, albumin and NLR for severe COVID-19." (PMID 33110593, 2020). "In another study that analyzed 167 confirmed patients with severe COVID-19, the LDH concentration was higher and the albumin concentration was lower in these patients, with significant differences." (PMID 33035175, 2020). "We observed substantial differences in the levels of proteins including PAB, ALB, GLB, and TP between patients who died of COVID-19 and those who recovered from the disease." (PMID 32671085, 2020). "OPLS-DA identified that the top five influencing parameters for COVID-19 severity were CRP, ALB, age ≥60 years, comorbidity, and lactate dehydrogenase (LDH) level." (PMID 33330318, 2020). "The top five parameters that influenced the severity of COVID-19 were CRP, ALB, age ≥60 years, comorbidity, and LDH." (PMID 33330318, 2020). "Correlation analysis and characteristic analysis showed that the LDH, PT, Cr, T-Bil, LYM%, ALB, NEUT%, and EOS% indicators had strong correlations with the prognosis of severe and critical patients with COVID-19 in the ICU." (PMID 33035175, 2020). "Given their routine adoption in clinical chemistry and role in COVID-19-related pulmonary pathophysiology, it makes perfect sense that our model selected LDH, leukocytes, bicarbonate, and albumin as the strongest predictors of our model." (PMID 33501388, 2020). "Commonly reported hepatic manifestations of COVID-19 include elevations in serum levels of alanine transaminase (ALT), aspartate transaminase (AST), and bilirubin, while levels of albumin are decreased." (PMID 32903492, 2020). "On the other hand, reduced concentrations of plasma albumin (such as IBD, ARDS and COVID-19) will induce elevated plasma levels of both free FFAs and bioavailable zinc." (PMID 32708755, 2020). "The results indicated that the levels of LYM, ALB, A/G, and CRP were significantly correlated with the severity of the COVID-19." (PMID 32746805, 2020). "Previous studies also reported that COVID-19 patients had a higher level of LDH and a lower level of lymphocyte count/percentage and albumin than healthy individuals." (PMID 33308159, 2020).
COVID-19 (continued). "In this meta-analysis, the laboratory findings revealed significantly lower levels of albumin and significantly higher levels of ALT and AST in COVID-19 patients; moreover, we also observed statistically insignificant higher levels of total bilirubin." (PMID 33194489, 2020). "Our results showed that sex was independently associated with abnormalities in six of the eight hepatic injury markers (TBil, DBil, albumin, ALT, AST, and GGT) and that adult male COVID-19 patients were more likely to have abnormal hepatic injury markers than female patients." (PMID 41574293, 2025). "Albumin of patients with COVID-19 was higher compared to severely ill patients not infected by this virus." (PMID 41233786, 2025). "Significantly reduced albumin levels are common in severe COVID-19 cases, but changes in albumin are not parallel to the severity of hepatocellular damage in COVID-19." (PMID 40143356, 2025). "As we show in the current study, combining information on CRP, albumin, RDW, and age in hospitalized COVID-19 patients results in a comprehensive, clinically relevant prognostic score that incorporates different aspects of thromboinflammation and chronic comorbidities." (PMID 40431641, 2025). "Albumin levels were significantly reduced in severe COVID-19 patients compared to both controls and the non-severe group (p < 0.001 and p = 0.006, respectively), consistent with a negative acute-phase response." (PMID 41154334, 2025). "We found that a positive correlation was between neopterin and CRP levels (r = 0.485, P < .001), while a negative correlation was between neopterin and albumin levels in patients with severe COVID-19 (r = 0.669, P < .001)." (PMID 39058886, 2024). "It was found that there was no independent correlation between ALT, AST, total bilirubin, alkaline phosphatase, albumin, and other indicators of liver function, and severe COVID-19, indicating that the liver was not the main target organ." (PMID 39372691, 2024). "Key biomarkers (CRP, ferritin, NLR, and albumin) exhibited distinct distributions across COVID-19 positive and negative cases." (PMID 39767161, 2024). "COVID-19 patients suffering from moderate or severe disease had raised CAR, NLR, urea, ANC, NMR, ferritin, fibrinogen, LDH, D-dimer, SGOT/AST, INR phosphorus and lower albumin, calcium, ALC, LMR, AEC, ABC, and platelet count levels." (PMID 38690475, 2024). "Another notable finding was that in the COVID-19 group, patients were diagnosed at a younger age and presented with better ECOG performance and nutritional statuses, as evidenced by serum hemoglobin and albumin levels." (PMID 39115263, 2024). "In a separate study involving 191 COVID-19 patients, non-survivor patients had a lower albumin level than survivors (P < 0.0001)." (PMID 37712883, 2024). "The present study investigated whether the D-dimer to albumin ratio (DAR) can predict the severity of illness and mortality in COVID-19 patients." (PMID 39144651, 2024). "Mean urinary protein-to-creatinine ratio and albumin-to-creatinine ratio were comparable between the patients with COVID-19 and those without COVID-19 (0.765 ± 1.36 vs. 0.58 ± 0.46 g/g, P = 0.292; and 187 ± 571 vs. 149 ± 233 mg/g, P = 0.595, respectively)." (PMID 38899195, 2024). "In COVID-19 patients, down-regulated FXR expression correlated with higher levels of immature neutrophils (bands), INR (blood clotting parameter), PT (blood clotting parameter), and GGT (liver enzyme) upon admission, alongside a higher albumin level." (PMID 38932276, 2024). "This research revealed a nonlinear relationship between the lowest value of albumin during hospitalization and adverse outcomes in the elderly with COVID-19." (PMID 39612427, 2024). "The correlation between the lowest level of serum albumin and adverse outcomes of COVID-19 is a nonlinear." (PMID 39612427, 2024).
COVID-19 (continued). "In a study on the mortality rate of COVID-19 concerning albumin, the findings revealed a negative correlation, with an increase in mortality rate as albumin levels decrease." (PMID 38195421, 2024). "We measured serum levels of sNOX2-dp, zonulin, LPS, D-dimer, and albumin in 175 patients with COVID-19, classified as having or not acute respiratory distress syndrome (ARDS), and 50 healthy subjects." (PMID 39456513, 2024). "The ratio between lactate and albumin has not been studied in critically ill patients with COVID-19." (PMID 39685564, 2024). "Patients with severe COVID-19 have elevated levels of AST, ALT, and GGT and reduced albumin levels." (PMID 37047897, 2023). "In the control group, there were no significant deviations in albumin values from the reference range of 3.5 to 5.2 g/dL, while in patients with COVID-19, albumin levels were outside the reference range." (PMID 36982882, 2023). "Our results showed that non-severe patients had a significantly increased albumin level compared to severe COVID-19 patients." (PMID 37554121, 2023). "Albumin and ratio of lymphocytes had powerful negative correlations with COVID-19 severity (RR values of 0.46 and 0.34, respectively; all P<.001), and the RR values were lower than the pooled RR (Multimedia Appendix 14 and Multimedia Appendix 15)." (PMID 36668902, 2023). "An additional finding of the ROC data shows that the NPV scores support the hypothesis that early normal-range blood parameters (i.e., CK-MB, TnT, FBG, AST, ALT, CK, CRP, albumin, and INR) in Omicron COVID-19 individuals might provide mild or light effects." (PMID 37110348, 2023). "Changes in hemoglobulin and albumin levels were also compared between patients with and without COVID-19." (PMID 37501590, 2023). "Non-significant alterations of serum bilirubin and serum albumin were found among participants before, during, and after COVID-19." (PMID 37312131, 2023). "For instance, patients with severe COVID-19 have higher CRP, D-dimer, and lactate dehydrogenase (LDH) levels but lower albumin levels than those with non-severe COVID-19." (PMID 37887751, 2023). "Indeed, we noticed this same pattern in our critical COVID-19 on VV-ECMO patients, with raised concentrations of G-GT and direct bilirubin, as well as lower concentration of serum albumin." (PMID 36617343, 2023). "Albumin levels were found to decrease rapidly following admission in patients with COVID-19 regardless of outcome, whereas the recovery in albumin levels predicted clinical improvement in this cohort." (PMID 37810906, 2023). "It was shown that male gender, severe COVID-19 and lactate dehydrogenase were significant positive predictors, while albumin level was a significant negative predictor of Brixia score." (PMID 37371019, 2023). "Therefore, the long-term follow-up protocol of care of COVID-19 survivors with T2D should include BMI, mean ABP, HBA1c, BUN, serum creatinine, eGFR, serum albumin, lipid profile, intact PTH, vitamin D3, ALP, serum calcium." (PMID 37312131, 2023). "In patients with COVID-19 with a confirmed severe clinical picture, lower values of serum albumin and vitamin D were recorded, as opposed to an elevated value of D-dimer." (PMID 37109161, 2023). "Statistically, significantly more patients without COVID-19 had high creatinine levels (38.6 vs. 19.5), low albumin levels (79.7 vs. 58.1), and high CRP levels (96.4 vs. 83.3) versus the SARS-CoV-2-positive patients." (PMID 36838400, 2023). "In our study, albumin and ratio of lymphocytes showed a strong negative correlation with COVID-19 severity." (PMID 36668902, 2023). "In another retrospective cohort study done in 1827 hospitalized patients, liver tests were abnormal in patients with COVID-19 both pre-hospitalization (AST 20.3%, ALT 19.1%, ALP 13.4%, TBIL 4.1%, albumin 27%) and peak hospitalization (AST 83.4%, ALT 61.6%, ALP 22.7%, TBIL 16.1%, albumin 86.6%)." (PMID 37082482, 2023).